GAPDH (glyceraldehyde-3-phosphate dehydrogenase)
Diseases named in the same sentence as GAPDH in open-access papers (continued):
Sharing a sentence is not in itself a finding about the gene and the disease.
tumor (continued). "GAPDH is a key enzyme in glycolysis that catalyzes the first step of the pathway by converting D-glyceraldehyde 3-phosphate (G3P) into 3-phospho-D-glyceroyl phosphate while glucose consumption is increased in most tumor cells, and glycolysis is therefore up-regulated (Warburg effect)." (PMID 35268705, 2022). "However, new evidence suggests that GAPDH may be overexpressed in cancer to boost glycolysis and accelerate tumor growth." (PMID 36276846, 2022). "Furthermore, orally administered HA exerted antitumor effects on subcutaneously grafted tumor cells via GAPDH inhibition in vivo, indicating that novel interactions occur between mutualistic bacteria and host tumors located in the distant gastrointestinal tract." (PMID 35459092, 2022). "Furthermore, we used regression coefficients for HERPUD1, MAP3K8, GAPDH, and DNAJB4 to construct risk score models as follows: risk score = −0.197∗MAP3K8 −0.261∗HERPUD1+ 0.185∗GAPDH+ 0.191∗DNAJB4 and calculated the risk score for each LUAD tumor sample." (PMID 34295900, 2021). "Taken together, these findings support the assertion that metabolism advantage with enrichment of GAPDH‐enriched cluster reshapes the hypoxia microenvironment and interplay between distinct subpopulations might enhance tumor malignant phenotypes and render worse prognosis." (PMID 34105295, 2021). "Therefore, based on the HER2 study, we have included GAPDH in the final validated assay to accommodate future applications where tumor cellularity may be low." (PMID 34858420, 2021). "Interestingly, PFK-1 showed an even higher protein expression level in malignant tumor tissues of overweight/obese women compared to malignant tumor tissue of normal-weight women, while GAPDH only showed an increased expression in malignant tumor tissues of overweight/obese women." (PMID 34073074, 2021). "Similarly, HK2 and GAPDH are key mediators of aerobic glycolysis and promote tumor growth." (PMID 32500034, 2020). "Likewise, Johanna and colleagues confirmed that DLBCL is a highly metabolically active tumor, and that the metabolic status of DLCBL can predict the efficacy of mitochondrial metabolism disruptors in DLCBL with low GAPDH, which causes a poor prognosis of patients treated with R-CHOP." (PMID 32570218, 2020). "Therefore, the inhibition of GAPDH was shown to be major anti-tumor mechanism and a novel target." (PMID 31612140, 2019). "Tumour masses from mice injected with UCP2 (genipin) and mTOR inhibitors (everolimus) revealed a strong reduction in tumour volume and number of mitosis, associated with a marked cytosolic glycolytic enzyme glyceraldehyde 3-phosphate dehydrogenase (GAPDH) nuclear positivity." (PMID 29587429, 2018). "Ratios of COX-2 mRNA expression in tumor/normal colorectal mucosa, normalized with respect to tissue weight, correlated best with the corresponding ratios normalized for B2M (R = 0.952; P < 0.0001), and to a lesser extent with those normalized for GAPDH (R = 0.830; P < 0.0001)." (PMID 24383454, 2014). "Thus, molecular targeting of GAPDH by tumor-specific delivery or inhibition could provide a viable therapeutic opportunity enabling us to overcome the current challenges in chemotherapy." (PMID 22964488, 2012). "Thus, the calculated cut-off value of survivin/GAPDH ratio of tumours was 5.2." (PMID 12373603, 2002). "Moreover, a comparison between PSBMA@threads and commercial silica membrane solid-phase extraction materials revealed that PSBMA@threads can extract DNA from 1 × 105 tumor cells for PCR amplification of GAPDH and CDH1, whereas the silica membrane purification column could not." (PMID 40573538, 2025). "For example, core glycolysis genes such as ALDOA, GAPDH, ENO1, and PKM2 are high in both tumor and immune cells." (PMID 39774001, 2025).
tumor (continued). "The expression of glycolytic genes HK2, GAPDH and ENO1 were analysed in the context of MYCN amplification, INSS tumour stage progression and overall event free survival using KM plots." (PMID 41420301, 2025). "The expression of MALAT1 in tumor cell lines (A431, A549, PC9GR, PC9) was evaluated using quantitative real-time PCR and normalized to the endogenous control GAPDH." (PMID 40597438, 2025). "This is achieved through GAPDH's interaction with the AKT signalling pathway, which promotes cell proliferation and tumor growth." (PMID 40491606, 2025). "To further validate the role of these metabolites in the antitumor effect, we conducted molecular docking studies to explore the interactions between differential metabolites in P. crataegi and core tumor targets such as SRC, GAPDH, and CASP3." (PMID 40877012, 2025). "Serotonin (5-HT)-mediated serotonylation of glyceraldehyde-3-phosphate dehydrogenase (GAPDH) drives the metabolic shift to glycolysis in CD8+ T cells, enhancing anti-tumor immunity." (PMID 40155378, 2025). "Previously characterized tumor cell lines were included as B7H6-positive (HCT15) and B7H6-negative (MDA.MB.231) controls, and GAPDH and GNB2L1 were used as internal control genes." (PMID 39708357, 2025). "Glycolysis genes HK1, GAPDH, ENO1, LDHA, and PKM, and cell cycle genes (except CCND2) were among the most tumor-specific genes." (PMID 39774001, 2025). "In a multivariable model adjusted for age, sex, H. pylori infection, histologic type, Lauren type, and tumor size, PPL/GAPDH (odds ratio 0.66 per 1 unit; p = 0.041) was the only statistically significant biomarker." (PMID 40429589, 2025). "Our study identified RRM2 and GAPDH as hypomethylated and upregulated genes in LUAD, suggesting that their hypomethylation leads to increased expression, contributing to enhanced tumor aggressiveness, drug resistance, and poor patient prognosis." (PMID 40341308, 2025). "The expression levels of GAPDH, FSCN1, SLC2A1, FAM83A, PLEK2, and GJB3 all presented significant differences between tumor tissues and normal tissues." (PMID 38370379, 2024). "A study demonstrated that BACH1 binds to the promoters of glycolytic genes, such as HK2 and glyceraldehyde-3-phosphate dehydrogenase (GAPDH), activating their expression and promoting the rate of glycolysis, thus facilitating tumor cell metastasis." (PMID 38408962, 2024). "We previously identified a new glyceraldehyde-3-phosphate dehydrogenase (GAPDH) inhibitor, DC-5163, which shows great potential in inhibiting tumor growth." (PMID 38811918, 2024). "This metabolism enrichment highlighted enzymes at the interface between glycolysis (GAPDH, ENO1, LDHA) and one-carbon metabolism (TYMS, SHMT2, MTHFR, MTHFD1), further confirming the importance of these two pathways in CIMP tumours." (PMID 38540202, 2024). "A four-gene signature, consisting of TYMS, GAPDH, TK1, and DHFR, was enough to diagnose the CIMP phenotype and identify tumours eligible for immunotherapy." (PMID 38540202, 2024). "The Wilcoxon rank sum test revealed that GAPDH expression was considerably higher in LUAD tumor samples than in normal samples, and similar results were observed when normal and tumor tissues from the same patient were analyzed together." (PMID 36837761, 2023). "In that study, normalization of HER2 levels to glyceraldehyde 3-phosphate dehydrogenase (GAPDH) improved concordance between immuno-MRM-MS and predicate assays for tumor classification." (PMID 37730181, 2023). "Alcohol dehydrogenase 1A (ADH1A), CAT, GAPDH, and MDH2 were related to the generation of precursor metabolites and energy, which played an important role in the proliferation of tumor cells." (PMID 37124724, 2023). "Although subcutaneous tumours did not cause gross pulmonary metastatic foci in our model (data not shown), higher micro‐metastasis of tumour cells was detected in hsa_circ_0057105 overexpression group, as determined by qRT‐PCR analysis of human GAPDH mRNA in mouse circulation." (PMID 37496319, 2023).
tumor (continued). "HK2, GAPDH, and PKM2 are the glycolytic enzymes, and elevated glycolysis is related to tumor progression and treatment resistance." (PMID 35742944, 2022). "In conclusion, GP5, CCT7, UQCRC1, PGD, GAPDH and LDHA have been found to play a role in tumor development, prognosis and even diagnosis in previous studies." (PMID 36404333, 2022). "Seven genes, PFKFB4, ALDOA, EGLN3, EHHADH, GAPDH, HMGCS2, and ENO2, related to tumor FDG uptake were revealed to have a good prognostic value for survival in HCC." (PMID 35174098, 2022). "Subsequently, we applied RT-PCR to detect the expression level of GAPDH, GNPNAT1, HTATIP2, MFI2, PKP2, RGS20, and CHRDL1 in these 10 tumor tissues." (PMID 35186082, 2022). "GPI1, TPI1, GAPDH, PGK1, and PKM2 were consistently upregulated in almost all tumor types, while PCK1, PCK2, and FBP1 were downregulated in tumors." (PMID 35246510, 2022). "Anoxia is one of the major phenomena during tumor growth and activates the HIF-1α transcription factor to upregulate GAPDH expression." (PMID 34650911, 2021). "On the one hand, Myc regulate the glycolytic process of tumor cells by activating glycolysis-related proteins such as HK2, glyceraldehyde-3-phosphate dehydrogenase (GAPDH), and enolase-1." (PMID 34976805, 2021). "This assay highlighted the heterogeneity in the expression of both GAPDH and RB1, confirming that CTCs represent a heterogeneous group of tumor cells." (PMID 33761970, 2021). "Glyceraldehyde-3-phosphate dehydrogenase (GAPDH) overexpression indicates a poor prognosis in early-stage NSCLC, and the assessment of glucose metabolism has certain prognostic value in this tumour." (PMID 34112123, 2021). "With the use of the human-specific GAPDH qRT-PCR method, we also assessed lung metastasis in the MDA-MB-436 orthotopic tumor-implantation model." (PMID 33575432, 2021). "The comparison of expressions of LDHA, GAPDH, and ENO1 showed overall higher expression in tumor samples as compared to the normal samples." (PMID 34831287, 2021). "Thresholds for tumor marker detection for Group1 were set from Group2 analysis (any hTERT, TERC/GAPDH 3.12, MYC/GAPDH 0.155)." (PMID 34790573, 2021). "Similarly, mitophagy in Warthin tumor oncocytes could be impaired solely by a reduction of cytoplasmic GAPDH levels rather than due to PKCδ-mediated phosphorylation; however, a role of PKCδ mediated GAPDH inactivation in Warthin tumor oncocytes cannot be excluded." (PMID 32365590, 2020). "3-Bromopyruvate (3BrPy) is a potent inhibitor of glyceraldehyde-3-phosphate dehydrogenase (GAPDH) and HK2 and can be selectively taken up into the cell via the highly expressed MCT1 lactate transporter in tumor cells." (PMID 32806533, 2020). "Due to our observation of substantial down‐regulation of ADAMTS9‐AS1 in tumour tissues compared to adjacent normal tissues, RT‐qPCR was used to verify ADAMTS9‐AS1 expression levels in CRC cell lines normalized to GAPDH." (PMID 32889785, 2020). "Using the GAPDH gene as reference, in the peritumoral area, we observed a significantly higher (almost 4 times) expression of SCD than in the growing tumor area (p = 0.015) and almost 3 times higher expression than in necrotic core (p = 0.019)." (PMID 32392704, 2020). "Among the four selected genes, ENO1, GAPDH, and SLC2A1 were significantly upregulated in tumor tissues compared with normal tissues." (PMID 32084009, 2020). "A closer look between accumulation of [89Zr]Zr-cetuximab within the tumor and total EGFR/GAPDH ratios revealed a strong positive correlation (r = 0.9461, p = 0.0011)." (PMID 32295603, 2020). "For 7 SCC-distinguishing enzymes (ASNS, GAPDH, GOT2, IDH2, ME1, PSAT, and TPI) protein levels were increased in MYC+N1ICD tumours compared with the normal lungs." (PMID 31114017, 2019). "Under low glucose conditions, the glycolytic enzyme glyceraldehyde-3-phosphate dehydrogenase (GAPDH) prevents the translation of IFN-γ, a key effector molecule in tumor-infiltrating cytotoxic T cells." (PMID 31083487, 2019).
tumor (continued). "The CA9 mRNA level was also correlated with the mRNA expression of other HIF1 target genes in the investigated tumor samples such as glucose transporter 1 (Glut1≙ SLC2A1), glyceraldehyde-3-phosphate dehydrogenase (GAPDH), VEGFa and with miRNA-210 expression." (PMID 30654595, 2019). "The inhibition of metabolic enzymes such as ALDOA, GAPDH or FASN can prevent or revert EMT in cell models, as can the neutralization of acidic tumor environments." (PMID 31277295, 2019). "The residual si-hVDAC1-TTs demonstrated a massive reduction in the expression of Glut-1, HK-I, GAPDH and LDH-A, fostering enhanced aerobic glycolysis in the untreated tumour." (PMID 30544833, 2018). "RPS5 in combination with RPS19 (for tumor tissues) or HNRNPH (for cell lines) showed the highest expression stability compared to other genes such as B2M and GAPDH, which are the most commonly used reference genes in many human and canine OS studies to date." (PMID 29178874, 2017). "ACT, GAPDH and TUBB, the three most commonly used reference proteins, all exhibited marked elevations in tumor samples." (PMID 27556505, 2016). "CVs of GAPDH, UBC and EEF1A1 across ischemia time points and patients in normal and tumor colorectal tissue." (PMID 26222051, 2015). "In order to evaluate and screen the optimal endogenous control for lncRNAs analysis of tissues and cells, the candidate reference genes (GAPDH, TBP, β-actin and HPRT1) were measured in 21-pair ESCC tumor tissues and adjacent normal tissues." (PMID 25608466, 2015). "All seven glucose metabolism-related proteins were downregulated in SBP1 induced-tumor tissue, including GAA, GAPDH, ALDH2, Thioredoxin, ENO3, UGDH and Lumican." (PMID 25974208, 2015). "In tumor tissue samples, the CV of EEF1A1 (6.12) was the second highest compared with UBC and GAPDH." (PMID 26222051, 2015). "The protein levels of GAPDH, Akt, TGF-β1, and α-SMA in tumor tissues decreased after being treated with Brucea javanica oil." (PMID 26508976, 2015). "In RINm5F rat tumor cells, the ADP ribosylation of GAPDH is enhanced by NO possibly because NO exhibits S-nitrosylating GAPDH function." (PMID 25859407, 2015). "Conversely, GAPDH and ACTB, the two most commonly reported normalization genes, did not fulfill the criteria of constant expression between normal and tumor samples, as already described by several authors for other malignancies." (PMID 25473950, 2014). "In this context, it is not advisable to blindly accept the best combination suggested by geNorm and NormFinder, as both algorithms included genes like GAPDH and H3F3A showing differences in expression level between normal and tumor endometrial tissues." (PMID 25473950, 2014). "This is supported in this study, where ATP5B, HSP60, GAPDH and PKM2 were all demonstrated to be significantly increased in the tumour epithelium, when compared to the stromal compartment in OAC tumour biopsies." (PMID 24968221, 2014). "When normalized to GAPDH, the means of Rab27b mRNA expression in CRC tissues and the corresponding tumor-adjacent tissues were 4.01 ± 0.301 and 1.50 ± 0.156, respectively (t = 7.429, P < 0.001)." (PMID 25580113, 2014). "Using GAPDH as normalization control, LOC285194 expression was significantly lower in tumor tissues compared with adjacent normal tissues (p < 0.001)." (PMID 23680400, 2013). "Using GAPDH as normalization control, we confirmed that LOC285194 expression was significantly lower in 81 tumor tissues compared with adjacent normal tissues (p < 0.001)." (PMID 23680400, 2013). "In vivo studies also confirm that ceramide is targeting GAPDH in CLL, as protein isolated from tumor tissue showed an overall decrease in GAPDH expression following treatment with C6-ceramide nanoliposomes." (PMID 24367685, 2013).
tumor (continued). "The human specific GAPDH and mouse specific GAPDH were expressed in the PCSD1 xenografts indicating the presence of both human and murine cells within the xenograft tumor." (PMID 22035283, 2011). "A strong positive correlation between regional CA9, LOX and GLUT1 mRNA transcript levels and FAZA retention was revealed in a human tumor model suggesting that these genes display high hypoxia-specificity in vivo and are superior to LDH and GAPDH." (PMID 21306648, 2011). "Among the HER2-amplified tumours, 43.3% (n=13) showed moderate HER2 amplification (HER2/GAPDH ratio 2.0–4.0) and 56.7% (n=17) a strong amplification (HER2/GAPDH ratio⩾4.0)." (PMID 21179039, 2011). "RNA was extracted from the tumor and the adjacent brain matter analyzed by qPCR for RANTES and two housekeeping genes (GAPDH and β-actin)." (PMID 21647415, 2011). "Total RNA was isolated from normal and tumour-derived tissues (N=22) and expression of FGFR3 mRNA was measured by quantitative real-time RT–PCR relative to GAPDH." (PMID 20234367, 2010). "The glycolytic enzymes hexokinase II and glyceraldehyde 3-phosphate dehydrogenase (Gapdh) were significantly reduced after HBO treatment, opposing the tumor specific metabolic glycolytic phenotype." (PMID 19636430, 2009). "Amongst seven commonly used classical housekeeping genes, we found that expression levels of ACTB, GAPDH, GUSB and 18S rRNA, significantly differed between tumor and normal tissues on the basis of the examination of raw CT values." (PMID 19257903, 2009). "In tumor tissue and/or normal mucosa, the four best normalization genes are ALAS, GAPDH, RPS18 and SHAD and the most stable combination of two genes is GAPDH-SHAD." (PMID 19650912, 2009). "PPIA showed |ΔCt| = 1.45 ± 0.17, and GAPDH and HPRT1 had the highest difference in |ΔCt| (on average) between normal and tumor samples: 2.42 ± 0.20 for GAPDH and 1.91 ± 0.21 for HPRT1." (PMID 19014639, 2008). "According to literature, extracellular GAPDH, also found in rat serum, inhibits spreading of COS-7 cells, while PGK is secreted by tumor cells and its activity is regulated by hypoxia." (PMID 18302751, 2008). "The overexpression of GAPDH in tumour samples is further highlighted by visualization of GAPDH normalized counts based on the TCGA data." (PMID 41175344, 2025). "The FC in gene expression of each marker in tumour samples relative to healthy controls was determined using the 2− ΔΔCt method normalised to the average of 7 housekeeping genes (YWHAZ, CYC1, SDHA, TBP, GAPDH, UBC and 18s RNA)." (PMID 41034696, 2025). "In our patient cohort higher GAPDH abundance was correlated with lower MG-H1 modification frequency, less sLG accumulation in tumor as well as lower GLO1 but not GLO2 levels." (PMID 40461450, 2025). "Under glucose stimulation, PCAF can acetylate lysine 254 of GAPDH, increasing GAPDH activity, while HDAC5 can deacetylate the corresponding site, reversing GAPDH activity, thereby regulating cellular metabolism and altering tumour cell growth." (PMID 39778006, 2025). "In tumour cells, some enzymes such as PFK, GAPDH, PGK and PK accumulate and translocate to the nucleus and other intracellular locations in response to stimuli, where they can regulate gene expression and interact with other proteins not involved in metabolism." (PMID 39904372, 2025). "Interestingly, analysis of EVs from 4T1 tumor-bearing mice demonstrated that the reserpine treatment resulted in EVs with less flotillin-1 (FLOT-1) and GAPDH bands of larger or smaller size compared to the other treatment conditions." (PMID 38405101, 2024). "Subsequently, tumor formation in the lungs was quantitated using photon counts measured by IVIS imaging (Eii), number of tumor nodules (Fig. 5Eiii,Eiv), and number of cancer cells measured by qPCR of human GAPDH gDNA." (PMID 38649663, 2024).